RNU6-999P (RNA, U6 small nuclear 999, pseudogene)
Gene: Small nuclear RNA gene on chromosome 1 (245,043,928 to 245,044,032, forward strand). Ensembl gene ENSG00000251754.
Homologues: Orthologues: chimpanzee U6 (98% identical), macaque U6 (91% identical), dog U6 (74% identical), rabbit U6 (70% identical), mouse Gm24128 (65% identical). Paralogues in human: RNU6-480P (84% identical), RNU6-616P (82% identical), RNU6-729P (82% identical), RNU6-16P (81% identical), RNU6-21P (81% identical), RNU6-33P (81% identical), RNU6-38P (81% identical), RNU6-42P (81% identical), RNU6-46P (81% identical), RNU6-490P (81% identical), RNU6-890P (81% identical), RNU6-1 (80% identical), and 1286 more.